RAB22A (RAB22A, member RAS oncogene family)
Diseases named in the same sentence as RAB22A in open-access papers (continued):
Sharing a sentence is not in itself a finding about the gene and the disease.
cancer (29 papers, 2014 to 2025). A tumor composed of atypical neoplastic, often pleomorphic cells that invade other tissues. "RAB22A is a member of the Rab family of small GTPases, and the oncogenic role of RAB22A is also observed in several types of cancer." (PMID 35912006, 2022). "Our findings provide a promising therapeutic strategy to prevent metastasis in a subset of cancer patients who are positive for the Rab22a1–38 fusion gene(s), as the Rab22a1–38 portion governs the metastasis-promoting function of Rab22a-NeoFs." (PMID 33568623, 2021). "We predicted target genes of miR-204-5p by Starbase 3.0, and RAB22A had been reported to involve in the progression of several cancers." (PMID 34012964, 2021). "Furthermore, RAB22A is a critical oncogene that has a crucial impact on the course of many different forms of cancer." (PMID 36936971, 2023). "A database-based pan-cancer expression analysis of RAB22A was performed." (PMID 36936971, 2023). "Studies have found that the RAB5 subfamily (including RAB5, RAB21, RAB22A, and RAB22B) is primarily involved in the endocytosis, transport, and metabolism of growth factor receptors and may thus be associated with cancer progression." (PMID 36936971, 2023). "RAB22A was highly expressed in 33 malignant tumors, including HCC." (PMID 36936971, 2023). "Thus, we further determined the effect of HA-mExo-miR204 on the expression of BCL2 and RAB22A in these cancer cells." (PMID 36231028, 2022). "The RAB22A level in tumor tissues and the STING level in serum may predict the response of cancer patients to chemoradiotherapy, and RAB22A renders tumor cells more sensitive to diABZI in mice by secreting more activated STING via R-EVs." (PMID 36280710, 2022). "In addition, many studies have confirmed that Rab22a is upregulated and closely related to the progress of various malignant tumors." (PMID 35757470, 2022). "Rab22a is significantly upregulated in a variety of malignant tumors." (PMID 35757470, 2022). "Therefore, the 1–10 a.a.-iRGD peptide disturbs the Rab22a-NeoF1 binding to both SmgGDS607 and PYK2, and then would in principle diminish lung metastasis in cancer patients who are positive for RAB22A-NeoF1 fusion gene." (PMID 33568623, 2021). "Likewise, several studies have described the influence of hypoxia on EVs of different cancer types: hypoxic EVs stimulate cancer angiogenesis via Wnt4, miR-135b and miR-23a, and invasion and metastasis through a processes mediated by RAB22A." (PMID 32183388, 2020). "Some Rabs, such as Rab1b, Rab4b, Rab10, Rab22a, Rab24, and Rab25, are dysregulated in many cancers." (PMID 24587032, 2014). "In addition, the production of triple-negative breast cancer-derived ectosomes along with the growth and metastasis of cancer cells were significantly suppressed after Rab22a inhibition, highlighting the anti-cancer therapeutic potential of targeting ectosome formation." (PMID 35927755, 2022). "Notably, RAB22A was shown to have pro-immunogenic functions in cancer cells." (PMID 34783622, 2021). "RAB22A belongs to the RAS oncogene family, and its abnormal overexpression is involved in the occurrence and progress of many cancers." (PMID 38431306, 2024). "In the present study, we first found that RAB22A was upregulated in HCC and various malignant tumors by analyzing multiple databases." (PMID 36936971, 2023). "The protein-coding gene RAB22A, a member of the RAS oncogene family, is amplified or overexpressed in certain cancers." (PMID 36936971, 2023). "The exosomal Rab22a-NeoF1 fusion protein functions in its negative recipient cells, such as activation of RhoA and Stat3 in cancer cells and macrophages, respectively, which is dependent on its binding partner PYK2 from its positive donor cells." (PMID 33568623, 2021).
cancer (continued). "PYK2 via binding to Rab22a-NeoF1 fusion protein is also enriched in exosomes, and the exosomal PYK2 induces RhoA activation in its recipient cancer cells negative for Rab22a-NeoF1 to promote migration, invasion, and lung metastases of these cancer cells." (PMID 33568623, 2021). "This phenomenon seems to be very striking, Rab22a-NeoF1 fusion protein may be limited in its negative recipient cancer cells as it is taken up by exosome endocytosis, and then it binds to PYK2 kinase that has a high efficiency to activate RhoA." (PMID 33568623, 2021). "Taken together, our results demonstrate that perturbation of the interaction between Rab22a-NeoF1 and PYK2 using the 1–10 a.a.-iRGD peptide abrogates the promotion of its negative recipient cancer cells metastasizing to lungs induced by Rab22a-NeoF1 fusion protein." (PMID 33568623, 2021).
tumor (29 papers, 2014 to 2025). "High expression of RAB22A in HCC was positively associated with tumor status (tumor-free vs. with tumor, p = 0.033), sex (female vs. male, p = 0.047), weight (≤ 70 vs. > 70, p = 0.012), and histological grade (grades 3 and 4 vs. grades 1 and 2, p = 0.031)." (PMID 36936971, 2023). "The results of our research are consistent with the previous reports that the overexpression of Rab22a is associated with tumor malignancy." (PMID 35757470, 2022). "We have previously revealed that miR-204 was capable of down-regulating multiple targets, such as BCL2 and RAB22A, in tumor cells." (PMID 36231028, 2022). "We further demonstrated the tumor-promoting effect of Rab22a with the PI3K/AKT/mTOR signaling pathway." (PMID 35757470, 2022). "In this study, in the form of a drug delivery formulation, synthetic miR-204 was again confirmed to be able to inhibit tumor growth in vitro and in vivo, and the expressions of BCL2 and RAB22A were significantly down-regulated in tumor tissue." (PMID 36231028, 2022). "We then detect the expression level of miR-204-5p and RAB22A with qPCR and WB, and confirmed that si-circ_0021205 increased the expression level of miR-204-5p and decreased RAB22A level in tumor tissues." (PMID 34012964, 2021). "The protein levels of RAB22A and Bcl2 in tumor tissues were measured by immunohistochemistry staining." (PMID 32618144, 2020). "A previous study reports that miR-203 is a tumor suppressor by mediating RAB22A, member RAS oncogene family (RAB22A) expression, and has correlation with the progression and carcinogenesis of OS." (PMID 28934958, 2017). "Increased expression of Rab22a was observed in advanced tumor stages (III, IV), indicating that expression of Rab22a was positively correlated with FIGO stage (P = 0.027)." (PMID 25460499, 2014). "In summary, the present study is the first to demonstrate a tumor suppressor role for the miR-373 by targeting Rab22A in human EOC." (PMID 25460499, 2014). "In addition, RAB22A is involved in a miRNA downregulation mechanism in which the overexpression of small GTPases promotes tumor growth and carcinogenesis." (PMID 36936971, 2023). "Moreover, mechanistic studies indicated that LINC01232 positively regulated the levels of RAB22A via sponging miR-204-3p to affect ccRCC tumour progression." (PMID 34783622, 2021). "Interestingly, Rab22A also contributes to exosome biogenesis and shedding from primary tumor cells and tumor metastasis." (PMID 27718357, 2016). "MiR-204-5p may act as a tumor-suppressor by targeting IL-8, SOX4, USP47 and RAB22A genes and regulating the apoptosis, proliferation, invasion and tumor progression in GC." (PMID 26172537, 2015). "In one study, RAB22A promoted the formation of extracellular vesicles containing STING, so that STING was transported to the tumor microenvironment." (PMID 38431306, 2024). "Their research revealed that UCA1 upregulates several tumour‐promoting genes such as CAMP responsive element‐binding protein 1 (CREB1), B‐cell lymphoma 2 (BCL2) and Ras‐related protein Rab‐22A (RAB22A) by sponging miR‐204‐5p, which is a tumour suppressor." (PMID 38506091, 2024). "And by using fluorescence in situ hybridization and immunoprecipitation, the specific presence of endogenous Rab22a-NeoF1 in ZOS/ZOS-M cell lines and tumor tissues was determined." (PMID 32839478, 2020). "SR-BI removal led to the diminished expression of RAB22a, SNAP25 and VPS25, which suggested reduced generation and secretion of tumor-derived extracellular vesicles." (PMID 30823658, 2019). "RAB22A can mediate EMT, promote tumor cell migration and lead to tumor progression." (PMID 38431306, 2024).
tumor (continued). "We previously reported that miR-204 could suppress tumor cell proliferation by down-regulating multiple targets, such as BCL2 and RAB22A." (PMID 36231028, 2022). "In addition, LINC01232 facilitates ccRCC tumour progression via sponging miR-204-5p and increasing RAB22A, suggesting the critical role of the LINC01232/miR-204-5p/RAB22A axis in ccRCC progression." (PMID 34783622, 2021). "Interestingly, another study found that RAB22A-mediated autophagosome containing STING fused with early endosomes, resulting in a new organelle, Rafeesome, which promoted the secretion of vesicles packaging STING into tumor microenvironment, thus mediating anti-tumor immunity." (PMID 38431306, 2024). "In addition, RAB22A inactivates RAB7 to suppress the fusion of Rafeesome with lysosome, and the inner vesicles bearing activated STING are secreted as R-EVs, which activate the IFNβ pathway in recipient cells in the tumor microenvironment to execute antitumor immunity." (PMID 36280710, 2022).
infection (9 papers, 2012 to 2026). The state of being infected such as from the introduction of a foreign agent such as serum, vaccine, antigenic substance or organism. "We found that endocytic Rabs are selectively recruited to the vacuole of T. cruzi, among them Rab22a, Rab5, and Rab21 right away after the infection followed by Rab7 and Rab39a at later times." (PMID 33194787, 2020). "In addition to LAMP-1, other regulators could also potentially contribute to regulate the fusion; Rab5A and Rab22A have been found to be associated with the stimulation of the maturation of phagosomes containing either Listeria or Mycobacteria during early infection." (PMID 30186773, 2018). "Indeed, we found the RAB22A gene to be upregulated in response to infection with mycobacteria." (PMID 26586179, 2015).
benign tumor (1 paper, 2014). "The expression of Rab22a protein was significantly up-regulated in EOC tissues when compared with those in benign tumor and normal ovarian tissues." (PMID 25460499, 2014).
RAB22A also shares sentences with these, for which no sentence is quoted: stomach cancer (2 papers); Arthritis (1); bile duct cancer (1); breast tumours (1); cholangiocarcinoma (1); cholangiohepatoma (1); COVID-19 (1); gingival fibromatosis (1); leukaemia (1); medullary thyroid carcinoma (1); monoclonal gammopathy of undetermined significance (1); multiple myeloma (1); neuroblastoma (1); non-alcoholic fatty liver disease (1); Obesity (1); prostate carcinoma (1); scrapie (1); small-cell osteosarcoma (1); thyroid follicular carcinoma (1); thyroid papillary carcinoma (1).